TLR4 (toll like receptor 4)
Diseases named in the same sentence as TLR4 in open-access papers (continued):
Sharing a sentence is not in itself a finding about the gene and the disease.
osteoporosis (continued). "In recent years, increasing numbers of studies have demonstrated that the Toll-like receptor 4 (TLR4)/nuclear factor-κB (NF-κB) pathway plays a pivotal role in the development of osteoporosis." (PMID 38504994, 2024). "Taken together, miR-137 can activate TLR4/NF-κB pathway, inhibit osteogenic differentiation, and thus exacerbate osteoporosis in the osteogenesis of hBMSCs." (PMID 37344864, 2023). "The inhibition of the TLR4/NF-κB pathway has the potential to impede the differentiation and maturation of osteoclasts, as well as regulate osteoblast differentiation, thereby mitigating the development of osteoporosis." (PMID 38504994, 2024). "This is the only study that reported the role of TLR4 and AP-1 in osteoporosis." (PMID 38504994, 2024). "Since osteoporosis is a metabolic and endocrine disorder, TLR4 may play an important role in the pathogenesis of this disease." (PMID 38504994, 2024). "Therefore, the exact role of TRIF-TRAM-IRF3 and the MAPKs/AP-1 pathways in the TLR4-related osteoporosis needs further investigation." (PMID 38504994, 2024). "Studies reported the clinical findings the clinical significance of TLR4 in osteoporosis." (PMID 38504994, 2024). "There are three included studies that reported the roles of ncRNAs-mediated TLR4 in osteoporosis." (PMID 38504994, 2024). "In summary, ncRNAs exhibit a key role in osteoporosis by regulating the expression of TLR4." (PMID 38504994, 2024). "TLR4, a receptor found on the surface of osteoclasts and osteoblasts, plays a crucial role in regulating the immune response in individuals with chronic inflammation, ultimately leading to the development of osteoporosis." (PMID 38504994, 2024). "Studies reported the treatments targeted by TLR4 in osteoporosis." (PMID 38504994, 2024). "Seven included studies reported the effects of TLR4/NF-κB signaling in osteoporosis development." (PMID 38504994, 2024). "It makes sense to assume that miR-137, via a particular medium, may promote the activation of the TLR4/NF-κB pathway and exacerbate the progression of osteoporosis." (PMID 37344864, 2023). "Future therapeutic strategies targeting TLR4 may provide a new insight for osteoporosis treatment." (PMID 38504994, 2024). "GGT1 is an activator of TLR4-mediated osteoclastogenesis, and GGT1 is overexpressed in transgenic mice exhibiting symptoms of osteoporosis." (PMID 40943102, 2025). "Ultimately, we determined that AR495 and the fermentation broth group can balance bone metabolism by inhibiting the RANK/RANKL/OPG system, as well as the RANKL/TRAF-6 and TLR4/MYD88 pathways, thereby alleviating osteoporosis." (PMID 39410150, 2024). "MiR-137 enhances the activity of the TLR4/NF-κB pathway by targeting KDM4A, thereby inhibiting the osteogenic differentiation of hBMSCs and exacerbating osteoporosis." (PMID 37344864, 2023). "In the present study, molecular docking analysis revealed that asiatic acid exhibited stronger binding affinities toward several osteoporosis-related proteins, including STAT3, PPARγ, NF-κB p105, COX-2, ESRα, TLR4, and NF-κB p65, compared to their native ligands." (PMID 41562931, 2026). "In addition to the TLR4/NF-κB pathway, proinflammatory effects, ncRNAs, and RUNX2, some other potential molecular mechanisms are also proposed for TLR4-mediated osteoporosis." (PMID 38504994, 2024). "Therefore, we speculate that miR-137 may activate TLR4/NF-κB pathway by targeting KDM4A, thereby inhibiting the osteogenic differentiation of mesenchymal stem cells and worsening osteoporosis." (PMID 37344864, 2023).
hyperuricemia (20 papers, 2018 to 2025). An abnormally high level of uric acid. "In animal studies, compounds and molecules that disrupt the mechanisms of NLRP3 inflammasome and TLR4 activation have been shown to decrease the production of these mediators, thereby attenuating renal damage caused by hyperuricaemia." (PMID 38041694, 2023). "Therefore, further in-depth studies are necessary to fully understand the specific role of the TLR4 signaling pathway in hyperuricaemia-associated renal abnormalities." (PMID 38041694, 2023). "Hyperuricemia triggers several inflammatory signaling pathways, with the TLR4/NF-κB axis being especially important in promoting the release of pro-inflammatory cytokines such as IL-1β, MCP-1, and TNF-α." (PMID 40963680, 2025). "In murine models, LLY-606 attenuates hyperuricemia-induced inflammation by inhibiting the TLR4/MyD88/NF-κB axis, reducing pro-inflammatory cytokine release and modulating the gut microbiota." (PMID 41141596, 2025). "Evidence indicates that prebiotics such as anserine and chicory ameliorate hyperuricemia primarily through gut microbiota modulation, with anserine mediating protective effects against renal inflammation and chicory alleviating the LPS/TLR4 axis." (PMID 40862113, 2025). "Probiotics and prebiotics were reported to reduce the levels of UA in hyperuricemia, regulating UA excretion and transportation, thereby inhibiting renal inflammation and inhibiting the TLR4/Myd88/NF-κB signaling pathway." (PMID 38674582, 2024). "The TLR4/MyD88/NF-κB and NLRP3 proteins are reported to be the major signalling pathways closely associated with renal inflammation caused by hyperuricemia." (PMID 36839325, 2023). "Expression of XOD and proteins associated with NLRP3 inflammasome signaling, such as TLR4, NF-κB, NLRP3 and IL-18, was increased in the liver tissues of mice suffering from hyperuricemia induced by yeast extract compared with those in the normal group." (PMID 37124197, 2023). "Both EH-JAP and EH-LEU can alleviate hyperuricaemia and kidney inflammation in mice with diet-induced hyperuricaemia, possibly by inhibiting the TLR4/MyD88/NF-κB signalling pathway, thereby inhibiting uric acid biosynthesis and promoting its excretion." (PMID 37908979, 2023). "TLR4 acts as a promoter in the inflammatory response chain and regulates many inflammatory cytokines in hyperuricemia." (PMID 34444825, 2021). "For example, in hyperuricemia mouse model, nuciferine inhibited renal inflammation through suppression of Toll-like receptor 4/myeloid differentiation factor 88/NF-κB signaling and a NOD-like receptor family, pyrin domain containing 3 (NLRP3) inflammasome." (PMID 30360404, 2018). "Therefore, targeted drug research focusing on TLR4 and the NLRP3 inflammasome is vital for addressing the complications associated with hyperuricaemia." (PMID 38041694, 2023). "Experiments in vivo and in vitro have shown that hyperuricemia may induce renal tubular injury mediated by epithelial-mesenchymal transition (EMT) through the activation of Wnt5a or the TLR4/NF-κB signaling pathway." (PMID 35156903, 2022). "Increases hypoxanthine phosphate ribose transferase expression.Inhibits the uric acid synthesis by activating uric acid transporter.Inhibits NLRP3 inflammasome and TLR4/MyD88/NF-κB pathway.Regulates the composition and abundance of gut microbiota during hyperuricemia and renal inflammation." (PMID 36506033, 2022). "Given that TLR4 and the NLRP3 inflammasome play a significant role in hyperuricaemia-related kidney injury, recent scientific efforts have been focusing on the development of drugs that specifically inhibit TLR4 and the NLRP3 inflammasome." (PMID 38041694, 2023). "In a rat study, treatment with 10% Fru for 6 weeks induced hyperuricemia, IR, and renal inflammation via activation of the NLRP3 inflammasome and the TLR4–MyD88 signaling pathway." (PMID 35495917, 2022).
hyperuricemia (continued). "Tuna oligopeptides ameliorate hyperuricemia and GA by reprogramming UA metabolic pathways, inhibiting NLRP3 inflammasome and TLR4/myeloid differentiation primary response 88/nuclear factor-kappa beta signaling pathway activation, and p65-nuclear factor-kappa beta phosphorylation." (PMID 40607437, 2025). "The molecular mechanism of its specific action may be related to the inhibition of the TLR4/MyD88 signaling pathway and the NLRP3 inflammasome activation, thereby reducing IL-1β production in high fructose-induced hyperuricaemia mice." (PMID 38041694, 2023). "Therefore, inhibiting the TLR4 and NLRP3 pathways effectively reduced the release of inflammatory cytokines and at the same time attenuated the renal damage of hyperuricemia." (PMID 34444825, 2021). "Given that anserine decreased the expression of TLR4/MyD88/NF-κB and NLRP3 and elevated Nrf2 and TIMP1 in hyperuricemic rats, we speculate that anserine improves overall kidney function by decreasing inflammation, oxidative stress and cellular damage in hyperuricemia." (PMID 36839325, 2023).
kidney injury (20 papers, 2019 to 2025). Trauma to the kidney. "The TLR4/MyD88 pathway has been recognized as a central link in the pathogenic process of systemic inflammation and high-fat exposure-induced kidney injury." (PMID 36230117, 2022). "There are potential preclinical evidences that TLR4 has a deleterious role in acute kidney injury as it triggers an inflammatory and dysfunctional immune response that exacerbates tissue injury." (PMID 36674930, 2023). "In fact, LPS endotoxemia also induces acute kidney injury via toll-like receptor 4 (TLR-4) activation, NFkB activation, oxidative stress, and cytokine production." (PMID 36615318, 2022). "FA has been shown potentially effective therapeutic agent in the acute kidney injury model of LPS stimulation through suppression of inflammatory events by inhibiting TLR-4 mediated NF-κB activation." (PMID 32308620, 2020). "Since S100A8/A9 can activate different receptors, such as TLR4, to promote leukocyte recruitment and secretion of proinflammatory cytokines, such as IL-6 and TNF-α, leading to kidney injury." (PMID 37547329, 2023).
peritonitis (20 papers, 2010 to 2024). Inflammation of the peritoneum (tissue that lines the abdominal wall and covers most of the organs in the abdomen). "Employing a peritonitis mouse model, we found that the deficiency of the tlr2/tlr4, myd88 and trif results in decreased neutrophil influx to peritoneal cavities of mice, indicative that in addition to MyD88, TRIF contributes to neutrophilia triggered by TLR4 engagement by Natterin." (PMID 35408954, 2022). "In a previously conducted study our group demonstrated that Tlr2−/− mice exhibited significantly higher TLR4 baseline levels in aortic tissue, increased pro-inflammatory mediator expression along with a loss of contractile function after 18 h in a Colon ascendens stent peritonitis model." (PMID 27109115, 2016). "A similar pattern was observed in lipopolysaccharide (LPS; a TLR4 agonist)-induced sterile peritonitis (Upper), albeit with a slight increase in GFP expression among Mφs and T cells (15% in Mφs and 10% in T cells at their peak)." (PMID 38923993, 2024). "A study has successfully demonstrated an up-regulation of TLR-2 and TLR4/myeloid differentiation factor 2 (TLR-4/MD-2) expression in hepatic and splenic macrophages of mice afflicted with experimental peritonitis induced by cecum ligation and puncture (CLP)." (PMID 38420121, 2024). "Subsequently, the effect of TLR4 inhibitor TAK 242 on the production of inflammatory cytokines in the peritoneal lavage fluid of LPS-induced peritonitis mice was tested." (PMID 34884814, 2021). "A similar observation in a peritonitis model was reported for TLR4 of which the expression on myeloid cells was protective while its expression on hepatocytes was deleterious." (PMID 24498223, 2014). "TLR4 and TLR9 are major receptors sensing pathogen-associated molecular patterns (PAMP) and damage-associated molecular patterns (DAMP) to regulate peritoneal immunity during CLP-induced peritonitis." (PMID 38827745, 2024). "Moreover, the anti-inflammatory activity and transcriptomics profile of the TLR4 inhibitor TAK 242 against LPS-induced peritonitis were also studied." (PMID 34884814, 2021). "Moreover, the TLR4 inhibitor TAK 242 is capable of suppressing the inflammatory response of LPS-induced peritonitis." (PMID 34884814, 2021). "Moreover, TLR4 inhibitor TAK 242 was used to investigate the effect of TLR4 on the transcriptomic profile of the peritoneum of LPS-induced peritonitis mice." (PMID 34884814, 2021). "Interestingly, substrates inducing TLR4-NF-κB signaling ameliorated symptoms in LPS endotoxemia and various peritonitis animal models." (PMID 30514828, 2018). "Acute self-resolving animal models of Toll-like receptor 4 (TLR4)-mediated inflammation such as peritonitis have been utilized widely to investigate the dynamics of leukocyte trafficking and the phenotypic changes of infiltrating cells that contribute to the resolution of inflammation." (PMID 26794131, 2016). "To understand the roles of TLR9 in these FRC subsets during peritonitis, we challenged the mice with ODN (a TLR9 agonist, 2.5 nmol/mouse, i.p.), LPS (a TLR4 agonist, 5mg/kg, i.p.), and CLP for 18 hours." (PMID 38827745, 2024). "A model of LPS-induced peritonitis in mice was established (LPS 10 mg/kg, i.p.), and the influence of TAK 242 (TLR4 inhibitor) on the level of inflammatory cytokines in mouse peritoneal lavage fluid was investigated by using an ELISA test." (PMID 34884814, 2021). "On the basis of the finding that knockdown of SLC15A3 decreased TLR4-dependent IL-6 and TNF-α production, SLC15A3 was found to increase in mice with peritonitis, which was positively related to the development of inflammation." (PMID 29991810, 2018). "We speculate that downregulation of Cox-2 through TLR-2/TLR-4 (via MyD88) in the lungs of Lactobacillus rhamnosus GG or Bifidobacterium longum treated mice may play a protective role in attenuating inflammation induced lung injury following systemic sepsis and peritonitis." (PMID 24830455, 2014).
peritonitis (continued). "In mouse CLP peritonitis models, TLR-2 and TLR-4 expressions were significantly upregulated in hepatic and splenic macrophages, in the lungs and liver as well as in the intestine when compared to sham mice." (PMID 24830455, 2014). "Similarly, TLR4 activation–dependent myeloid-to-lymphatic transition can give rise to LEC precursors and promote inflammatory lymphangiogenesis in peritonitis mice." (PMID 38587075, 2024). "The Tlr4−/− mice did not develop PID or peritonitis when infused intra-peritoneal with vehicle or LPS." (PMID 20877575, 2010). "Similarly, blocking TLR4 at the onset of infection induced mortality from otherwise non-lethal peritonitis, while therapeutic administration of anti-TLR4 antibodies protected mice from lethal Gram-negative bacterial sepsis." (PMID 35990654, 2022). "In an acute model of sterile inflammation using a murine model of pristane-induced peritonitis the IFN-I signaling was responsible for monocyte recruitment and maturation during inflammation while mice deficient in TLR4, TNFα, IL-6, and IL1R failed to accumulate monocytes in the peritoneal cavity." (PMID 33995391, 2021). "However, to the best of our knowledge, the effect of TLR4 (Toll-like receptor 4) inhibitor on the transcriptomics of LPS-mediated mouse peritonitis has not been reported yet." (PMID 34884814, 2021). "On one hand, the expansion of HSCs from TLR4−/− mice to LPS was absent; on the other hand, those mice showed unchanged response to CLP and peritonitis." (PMID 26272069, 2015). "Here, we identify the closely related STIM2 as mediator of cell migration and cytokine production downstream of GPCR and TLR4 activation in macrophages and show that mice lacking STIM2 are partially resistant to inflammatory responses in peritonitis and LPS-induced inflammation." (PMID 26417434, 2015).
pulmonary tuberculosis (20 papers, 2012 to 2025). A bacterial infection that affects the lungs and is caused by Mycobacterium tuberculosis. "A recent meta-analysis revealed that the TLR4 polymorphic locus rs10759932, which is located in an upstream regulatory region of the TLR4 gene, increased the risk of pulmonary tuberculosis." (PMID 41295183, 2025). "Polymorphic loci rs5743708 (TLR2) influence the risk of developing LTBI and subsequent pulmonary tuberculosis in the Chinese population, and variations in rs7873784 (TLR4) and rs5743836 (TLR9) influence the risk of developing LTBI and pulmonary tuberculosis." (PMID 39339847, 2024). "It has been reported that TLR4 rs4986790A/G (Asp299Gly) and rs4986791C/T (Thr399Ile) SNPs were associated with susceptibility to pulmonary TB in an Iranian population." (PMID 30167433, 2018). "The present study was undertaken to explore the relationship of Toll-like receptor (TLR) 2, TLR4 genes polymorphisms with Pulmonary tuberculosis (PTB) risk in a sample of Chinese population." (PMID 29348888, 2017). "In the present study, we explored the genetic polymorphisms of IL-17, TLR4 and miR-146a in association with pulmonary tuberculosis in a Chinese Han population." (PMID 27339100, 2016). "In this population-based case control study, we explored the genetic polymorphisms of IL-17, TLR4 and miR-146a in association with pulmonary tuberculosis in a Chinese Han population." (PMID 27339100, 2016). "The aim of the present study was to investigate the potential association between pulmonary TB, a TB infection of the lungs, and three SNPs in TLR4 and TLR9 genes in southeastern Iranian population, Zahedan." (PMID 23766695, 2013). "TLR-4 mutant (C3H/HeJ) mice intranasally infected with live Mtb were more susceptible to pathogen and development of pulmonary tuberculosis relative to wild-type (C3H/HeN) mice, suggesting that TLR-4 may play a protective role in host defense against lung infection by Mtb." (PMID 22570668, 2012). "The present study revealed the synergic effect of TI,II/CC genotypes of TLR4 Thr399Ile and TLR9 T-1486C polymorphisms with the increasing risk of pulmonary TB." (PMID 23766695, 2013). "Variants in TLR4, Asp299Gly and Thr399Ile, and the TLR9-1486C/T were investigated for their association with susceptibility or resistance to pulmonary tuberculosis." (PMID 23766695, 2013). "We carried out a case–control association community based study, genotyping 12 polymorphisms of TLR2, TLR4, TLR6 and TLR9 genes in 90 patients with confirmed pulmonary TB and 90 unrelated exposed but asymptomatic household contacts." (PMID 24053111, 2013). "TLR4 has a protective role in adaptive immunity against pulmonary TB in vivo; the non-functional TLR4 causes high mortality and increased bacterial burden in the lungs." (PMID 36389170, 2022). "The analysis revealed the association of TLR2 “CC” genotype (rs3804100C/T) and TLR9 “TC” genotype (rs5743836) with LTBI susceptibility and TLR2 “GA” genotype (rs5743708A/G), TLR4 “GG” genotype (rs7873784C/G) and TLR8 “CC” genotype (rs3764879C/G) with susceptibility to pulmonary TB." (PMID 30167433, 2018). "Interestingly, up-regulation of TLR4 mRNA in mononuclear leukocytes has been described in patients with active pulmonary tuberculosis." (PMID 27458573, 2016). "Therefore, to determine whether TLR4 and TLR9 are associated with susceptibility to pulmonary TB in the current study, two common TLR4 polymorphisms, Asp299Gly and Thr399Ile, and one well-known TLR9 gene polymorphism, T-1486C, were examined." (PMID 23766695, 2013). "Therefore, we examined whether polymorphisms in TLR2, TLR4, TLR6 and TLR9 are associated with the susceptibility to pulmonary TB in Mexican individuals from a rural area with high incidence of TB." (PMID 24053111, 2013).
pulmonary tuberculosis (continued). "Our study identified unique gene signatures (IL-27, STAT1, IRF1, TLR4, IL-15, IL-2RA, IL-24, TGFβ, CD28, CD80, NFATC1, and PTGDR2) that discriminate active pulmonary TB from uninfected controls using unstimulated PBMCs." (PMID 37460564, 2023). "In active pulmonary TB patients with high bacterial burden, miR-23a-3p expression was decreased, affecting the balance between TLR4 and IL10 immunologic responses by down-regulating SP1/IRF1 expression and further influencing TLR4/IL10 expression ratio." (PMID 33202583, 2020).